TRPA1 (transient receptor potential cation channel subfamily A member 1)
Diseases named in the same sentence as TRPA1 in open-access papers (continued):
Sharing a sentence is not in itself a finding about the gene and the disease.
neuropathic pain (10 papers, 2016 to 2025). Chronic pain caused by damage to nerve fibers. "Of interest, it was reported that genetic variants of the TRPA1 gene, among others, were found in familial TN subjects, thus highlighting their involvement in neuropathic pain." (PMID 40363691, 2025). "The influence of neuropathic pain on the association of TRPA1 channels with opioid receptors and NMDARs was also evaluated." (PMID 33379368, 2020). "In SNI neuropathic pain, nerve injury also significantly increased the proportion of TRPA1+ DRG neurons responding to low dose AITC." (PMID 36477832, 2023). "Although TRPA1 and α2δ1 are co-involved in the occurrence and development of neuropathic pain, TRPA1 has different cellular localization and functional characteristics." (PMID 34658790, 2021). "In the oxaliplatin-induced model of neuropathic pain, neurons are directly affected by OXPT, which induces central and peripheral sensitization as a consequence of upregulation of TRPM8 and TRPA1 and downregulation of Kv4.3 neuronal channels." (PMID 37895952, 2023). "Our findings show the involvement of both TRPA1 and TRPV1 channels in trigeminal neuropathic pain, and in particular, in trigeminal mechanical allodynia." (PMID 30366396, 2018). "Our results suggest that TRPM8 and TRPM8-mediated membrane depolarization, but not TRPA1 or TRPV1, serve as the initial ionic/membrane drives that contribute to the development of oxaliplatin-induced neuropathic pain." (PMID 34149356, 2021).
pancreatic adenocarcinoma (10 papers, 2021 to 2024). "Although important in the context of modulation by 4-HNE of the cell migration and cell cycle in pancreatic adenocarcinoma, this study only shows the effects in cells that express TRPA1." (PMID 38543130, 2024). "From studies on cell cultures, we know that TRPA1 expression is elevated in pancreatic adenocarcinoma, nasopharyngeal carcinoma, osteosarcoma, metastatic colorectal carcinoma and glioblastoma." (PMID 39770499, 2024). "One recent study reported the endogenous expression of TRPA1 channels in human pancreatic adenocarcinoma cell lines and siRNA-induced downregulation of TRPA1 can enhance cell migration and change the cell cycle progression." (PMID 35614079, 2022). "This work reports the endogenous expression of TRPA1 channels in human pancreatic adenocarcinoma cell lines and provides insights into the function of the TRPA1 protein in the Panc-1 cell line." (PMID 33479347, 2021). "The results of this new study on TRPA1 expression in pancreatic adenocarcinoma cell lines provide insights into the function of TRPA1 channels in cancer and their putative role as participants to the cancerogenic process via channel-independent mechanisms." (PMID 33479347, 2021). "Additionally, 4-HNE, a product from lipid peroxidation, activates TRPA1 in pancreatic adenocarcinoma by redox modification of the free thiol groups." (PMID 39770499, 2024). "The specific inhibitor of TRPA1, A967079, promoted cell migration in pancreatic adenocarcinoma." (PMID 39770499, 2024). "In human pancreatic adenocarcinoma cell lines, robust functional TRPA1 expression was demonstrated." (PMID 37240443, 2023). "However, in pancreatic adenocarcinoma cells, the process is different: downregulating TRPA1 with siRNA, decreased cellular viability, and possibly, apoptosis, as revealed by cell cycle analysis." (PMID 37507867, 2023). "In a previous study on pancreatic adenocarcinoma patients, we presented the analysis of many TRP channels, including TRPA1." (PMID 39770499, 2024). "Our previous research demonstrated that TRPA1 plays a significant role in the FGFR2c-mediated enhancement of EMT and invasion in the context of pancreatic adenocarcinoma." (PMID 39596152, 2024). "Our previous studies showed that pancreatic adenocarcinoma cell lines express higher levels of the TRPA1 gene and protein than a non-tumoral pancreatic ductal cell line." (PMID 38543130, 2024).
pancreatitis (10 papers, 2011 to 2022). Inflammation of the pancreas. "Here, we have identified a remarkable downregulation of TRPA1 in ahPSCs and analysed its pathophysiological consequences in relation to pancreatitis." (PMID 36038551, 2022). "Selective TRPV1 and TRPA1 antagonists reduce pain and inflammation in murine models of pancreatitis." (PMID 32824721, 2020). "It has also been found that TRPA1 mediates inflammation, hyperalgesia and visceral hypersensitivity in pancreatitis pain as well as in a model of acute gout." (PMID 27315798, 2016). "We therefore decided to test it in a more specific preclinical pain model that relies on both, TRPV4 and TRPA1, in order to establish proof-of-principle that a dual-inhibitor can effectively treat pain and inflammation in pancreatitis." (PMID 27247148, 2016). "Similar data have been obtained in the case of caerulein-induced pancreatitis, where TRPA1 antagonists and genetic removal of TRPA1 (TRPA1 KO mouse) have been shown to reduce the extent of inflammation and pain in this model." (PMID 25640188, 2015). "The clinical observation that an antioxidant afforded protection in patients with pancreatitis indirectly supports the role of the oxidative stress sensor, TRPA1, in this condition." (PMID 23941062, 2013). "It has also been found that TRPA1 mediates ongoing nociception in chronic pancreatitis, and that both TRPV1 and TRPA1 initiate key pathways to transform acute into chronic inflammation and hyperalgesia in pancreatitis." (PMID 23941062, 2013). "The pancreatitis evoked by caerulein is likewise ameliorated by TRPA1 deletion, as is the activation of spinal neurons and the pain behavior that accompany pancreatitis." (PMID 21420431, 2011). "TRPA1 blockers may also be of use in pancreatitis and inflammatory bowel disease." (PMID 21420431, 2011).
allergic contact dermatitis (9 papers, 2017 to 2025). An inflammatory skin condition caused by an immune response to direct contact between the skin and an allergen. "It has also been shown that TRPA1‐deficient animals have reduced expression of inflammatory cytokines in experimental models of allergic contact dermatitis." (PMID 40329600, 2025). "TRPA1 mediates inflammation and scratching associated with allergic contact dermatitis; these symptoms can be mitigated by the genetic ablation of the TRPA1 gene or the administration of the TRPA1 channel antagonists HC030031 and A-967079." (PMID 33117171, 2020). "To determine the significance of the TRPA1 channel on allergic contact dermatitis, we isolated the back skin of mice and used HE staining to examine pathological reactions after administering HC030031." (PMID 28240277, 2017). "In addition, our recent work found that IL-33 released by keratinocytes can activate peripheral sensory neurons via promoting Ca2+ influx through TRPA1/TRPV1 channels in ST2 dependent mechanism, resulting in potentiation of skin inflammation and pruritus in a mouse allergic contact dermatitis model." (PMID 33204337, 2020).
Arrhythmia (9 papers, 2011 to 2025). Any cardiac rhythm other than the normal sinus rhythm. "Furthermore, previous reports stated that the activation of TRPA1 mediates the production of airway inflammation, causing lung inflammation, which increases the risk of arrhythmia to some extent." (PMID 32903613, 2020). "Recent research reported that exposure to acrolein increased heart rate (HR) variability and the incidence of arrhythmias in WT mice, while these consequences were eliminated in TRPA1−/− mice." (PMID 31680989, 2019). "We recently showed that TRPA1 mediates the increased sensitivity to aconitine-induced arrhythmia after diesel exhaust exposure." (PMID 25944145, 2015). "In an animal model, diesel exhaust increased the sensitivity of the heart to triggered arrhythmias via an activation of airway sensory receptors [e.g., TRPA1 (transient receptor potential cation channel A1)]." (PMID 21896397, 2012). "Treatment with the TRPA1 antagonist or sympathetic blockade lowered the LF/HF ratio and prevented wDE-induced arrhythmia sensitivity." (PMID 21377951, 2011). "Pretreatment of low wDE–exposed rats with a TRPA1 antagonist or sympathetic blockade prevented the heightened sensitivity to arrhythmia." (PMID 21377951, 2011). "The activation of TRPA1 indirectly promotes the occurrence of arrhythmia." (PMID 32903613, 2020). "Furthermore, acrolein, a smoke component, increases the heart rate variability and arrhythmia in mice, and this effect disappears after knocking out the TRPA1 gene or giving TRPA1 inhibitors." (PMID 32903613, 2020). "Moreover, our group has shown that increases in sensitivity to aconitine-induced arrhythmia after diesel exhaust exposure is dependent on the activation of TRPA1 on airway sensory nerves." (PMID 22138703, 2012). "We hypothesized that a single exposure to wDE would sensitize the heart to aconitine-induced arrhythmia, a response that could be prevented by blocking TRPA1 (and possibly TRPV1) or by sympathetic modulation." (PMID 21377951, 2011). "Decreased ST segment length in response to wDE was prevented by both TRPA1 and sympathetic blockade, suggesting that the shorter duration of repolarization after wDE may also contribute to greater arrhythmia sensitivity." (PMID 21377951, 2011). "In the present study, we indirectly examined the role of airway C-fibers in increasing the sensitivity of animals to aconitine-induced arrhythmia after exposure to wDE by testing the involvement of TRPA1 and TRPV1 ion channels, which are the chemical-sensing structures colocalized to these fibers." (PMID 21377951, 2011). "Finally, our future experiments will seek to determine if TRPA1 mediates heightened sensitivity to arrhythmia in animals exposed to filtered DE; this would clarify whether the gases in wDE drive this response." (PMID 21377951, 2011). "The presented results regarding infarct size do not allow conclusions concerning a role of TRPA1 in arrhythmia, as indicated by prior studies." (PMID 36768836, 2023). "It was not entirely a surprise that TRPA1 antagonism prevented the wDE-induced heightened sensitivity to arrhythmia." (PMID 21377951, 2011).
glioma (9 papers, 2015 to 2025). A benign or malignant brain and spinal cord tumor that arises from glial cells (astrocytes, oligodendrocytes, ependymal cells). "A recent study showed that activating TRPA1 in glioma cells leads to mitochondrial damage and cell apoptosis and decreases TMZ resistance." (PMID 37507867, 2023). "Activation of TRPA1 in glioma cells significantly decreased antioxidant expression and increased mitochondrial ROS production." (PMID 37507867, 2023). "Our results indicated that all hub genes were differentially expressed in glioma grade except TRPA1." (PMID 35625048, 2022). "The present study proved that activating TRPA1 in glioma cells, which leads to mitochondrial damage and dysfunction and ultimately to apoptosis, may decrease the TMZ resistance of GBM cells." (PMID 35982414, 2022). "Hence, in the present study, we hypothesized that activating TRPA1 in glioma cells, which leads to mitochondrial damage and dysfunction and ultimately to cell apoptosis, may decrease the TMZ resistance of GBM cells." (PMID 35982414, 2022). "The data showed that pretreatment of glioma cells with TRPA1 agonist increased pro-apoptotic protein (caspase-3/caspase-9, BAX) and decreased the level of anti-apoptotic protein (Bcl-2) compared to pre-treatment with the TRPA1 inhibitor." (PMID 40813985, 2025). "The effects were reversed by pretreatment of glioma cells with the TRPA1 antagonist, as opposed to the temozolomide (TMZ) therapy, which had a lower impact on the production of mitochondrial ROS and cell apoptosis." (PMID 37507867, 2023). "In glioma cells under hypoxia, ALA likely acts as an antioxidant agent, upregulating GSH and GSH-Px and down-regulating mitochondrial ROS production, thus blocking TRPA1-mediated induction of apoptotic cell death." (PMID 33928077, 2021). "This suggests that targeting and activating TRPA1 or targeting TRPV1 in glioma exhibiting such expression, can restore apoptotic signaling and might provide new insights for the development of alternative therapies against glioma progression." (PMID 33928077, 2021). "Specifically, two different glioma cell lines, U251 and SHG-44 were treated with TMZ, in combination with or without a TRPA1 agonist (PF-4840154) or inhibitor (HC030031)." (PMID 40813985, 2025).
multiple sclerosis (9 papers, 2019 to 2023). A progressive autoimmune disorder affecting the central nervous system resulting in demyelination. "However, whether TRPA1 is solely implicated in pain-signaling or contributes to neuroinflammation in multiple sclerosis (MS) is unknown." (PMID 37296632, 2023). "Interestingly, TRPA1 in astrocytes is implicated to partially contribute to cuprizone-induced demyelination, which is frequently used for the animal model of multiple sclerosis, raising the possibility that there is a connection between TRPA1 expression or function and psychiatric disorders." (PMID 33644051, 2021). "Our results indicate that there is no direct effect on OPC survival and proliferation but that the presence of endogenous TRPA1 agonists would impede remyelination in demyelinating lesions occurring in Multiple Sclerosis or other neurodegenerative diseases." (PMID 36762504, 2023). "Expression of TRPA1 has been reported in various brain areas where it seems to play a modulatory role in neurodegenerative disorders and neuroinflammation, such as multiple sclerosis, Alzheimer’s (AD), and Parkinson’s (PD) diseases." (PMID 35562920, 2022). "Discovery of TRPA1 antagonists can be a promising tool in treating various diseases, including neuropathic pain, inflammation, and multiple sclerosis." (PMID 31480671, 2019). "Quantitative structure-activity relationship (QSAR) and molecular docking studies have recently reported that the use of TRPA1 inhibitors could be an important treatment strategy for multiple sclerosis." (PMID 34912298, 2021). "Therefore, only 97 candidates (P > 0.5) were identified as potential TRPA1 antagonists with possible use in treating multiple sclerosis." (PMID 31480671, 2019). "In 2018, Flex Pharma published the first results of an exploratory Phase 2 study for multiple sclerosis of FLX-787, a TRPA1/TRPV1 co-activator." (PMID 35877758, 2022).
neuroblastoma (9 papers, 2010 to 2023). Neuroblastoma (NB) is the most common solid, extracranial childhood tumor. "We identified a TRPA1 (transient receptor potential A1) variant with increased sensitivity and differential modulation of channels by a tyrosine kinase inhibitor in neuroblastoma cells." (PMID 24975826, 2014). "TRPA1 expression and functional activity have also been reported in human uveal melanoma 92.1 cells, human neuroblastoma IMR-32 cells, and human oral squamous cell carcinoma (OSCC) samples." (PMID 37174661, 2023). "We postulated that EGb 761 would modulate TRPA1 channels, thereby exhibiting anti-inflammatory and neuroprotective effects in a neuroblastoma cell line." (PMID 37744878, 2023). "We found expression of ASIC1a, TRPV1, and TRPA1 channels in dopaminergic neuron-like cells derived from the neuroblastoma SH-SY5Y." (PMID 38203538, 2023). "We investigated acid-sensing (ASIC) and transient receptor potential vanilloid-1 (TRPV1) and ankyrin-1 (TRPA1) ion channels present in untreated and differentiated neuroblastoma SH-SY5Y to propose a new means for their study in neuronal-like cells." (PMID 35205034, 2022). "This is the first study to report expression of modified human TRPM8 or TRPA1 proteins in human SH-SY5Y neuroblastoma cells and we present several significant findings." (PMID 24975826, 2014). "In this study, we used site-directed mutagenesis, recombinant DNA engineering and measurements of agonist-induced Ca2+ influx to characterize TRPM8 and TRPA1 channel function in neuroblastoma cell culture." (PMID 24975826, 2014). "Interestingly, TMZ induced apoptosis in SH-SY5Y neuroblastoma cells via the ROS-dependent activation of TRPA1 followed by mitochondrial dysfunction and caspase activation." (PMID 37174661, 2023). "In other solid malignancies, including glioblastoma and neuroblastoma, ROS-induced TRPA1 activation results in a persistent increase in [Ca2+]i that causes mitochondrial Ca2+ overload and damage, thereby leading to caspase 3 activation and apoptotic cell death." (PMID 37174661, 2023). "To investigate whether TRPA1 can be activated by heat and cold under close-to-native conditions, we used F11 neuroblastoma cells derived from dorsal root ganglia neurons, which provide a well-characterized cellular model of peripheral sensory neurons." (PMID 31878344, 2019). "Therefore DNA expression constructs containing human TRPM8 or TRPA1 cDNAs were transfected into HEK (human embryonic kidney cells)-293 or SH-SY5Y neuroblastoma cells and G418 resistant clones analysed for effects of agonists and antagonists on intracellular Ca2+ levels." (PMID 24975826, 2014). "Likewise, TRPA1 was found to mediate oxidative stress-dependent caspase-3 activation and apoptosis in temozolomide-treated SH-SY5Y neuroblastoma cells and in mouse retina undergoing ischemia-reperfusion injury." (PMID 37393347, 2023). "To confirm the suitability of the differentiated neuroblastoma cell model for testing peptides that modulate TRPV1 and TRPA1 channel activity, we determined the levels of mRNA transcripts for TRPV1, TRPA1, and ASIC1a after 10 days of differentiation with RA + BDNF." (PMID 38203538, 2023). "In electrophysiological measurements, we did not observe any response to selective TRPV1 and TRPA1 agonists in RA-treated neuroblastoma cells." (PMID 35205034, 2022). "In the present research, we examined RA-treated human neuroblastoma SH-SY5Y in comparison with its untreated counterpart as a prospective in vitro model system to study native acid-sensing, transient receptor potential vanilloid-1 (TRPV1) and ankyrin-1 (TRPA1) ion channels." (PMID 35205034, 2022). "Similarly, a recent study showed that overexpression of TRPA1 in neuroblastoma cell lines also does not confer novel mechanical sensitivity or induce any changes in endogenous mechanically-evoked currents in these heterologous cells." (PMID 20808441, 2010).
neuroblastoma (continued). "Therefore, untreated and RA-treated neuroblastoma SH-SY5Y cells are not a suitable model for the study of TRPV1 and TRPA1." (PMID 35205034, 2022). "In this respect, SH-SY5Y cells, a human neuroblastoma line capable of neurotransmitter biosynthesis and in vitro neuronal dendrite extension, were recently stably transfected with TRPV1, but studies with TRPM8 and TRPA1 have not been reported previously." (PMID 24975826, 2014).